EPHB2 (EPH receptor B2)
Diseases named in the same sentence as EPHB2 in open-access papers (continued):
Sharing a sentence is not in itself a finding about the gene and the disease.
Alzheimer disease (10 papers, 2013 to 2024). A progressive, neurodegenerative disease characterized by loss of function and death of nerve cells in several areas of the brain leading to loss of cognitive function such as memory and language. "Moreover, it has been shown that Alzheimer disease-linked amyloid-β oligomers bind to the fibronectin domains of EphB2 and trigger receptor degradation in the proteasome." (PMID 34638814, 2021). "Increased EPHA4 signaling but decreased EPHB2 signaling have been reported to exacerbate Alzheimer’s disease pathology in mouse models." (PMID 39706267, 2024). "EphB2 is considered a neuroprotective factor for hippocampal neurons with a potential therapeutic role in Alzheimer's disease." (PMID 28337120, 2017). "In patients with Alzheimer's disease (AD) and in mouse models of AD, a reduction in the hippocampal EphB2 level is observed." (PMID 27419051, 2016). "EPHB2 is not only involved in glutamatergic neurotransmission but also simultaneously participates in the inflammation regulation process in some brain diseases including stroke, anxiety and Alzheimer’s disease." (PMID 31920518, 2019). "Thus, augmenting EphB2 activity could have beneficial effects in Alzheimer disease by reversing long-term potentiation impairments." (PMID 34638814, 2021). "Disruption of the EphB—NMDAR interaction in models of Alzheimer disease or in NMDAR encephalitis that results in reduced surface levels of NMDAR may involve the FN3 domain of the EphB2 protein, further supporting the importance of understanding phosphorylation of these domains." (PMID 28719605, 2017). "The important functions of EphB2 include regulation of NMDAR-dependent Ca2+ influx and downstream transcription factors in neuronal cells, and the involvement in neurological diseases, including Alzheimer’s disease, anxiety, and anti-NMDA encephalitis has been reported." (PMID 24139226, 2013).
cervical cancer (10 papers, 2015 to 2026). A primary or metastatic malignant neoplasm involving the cervix. "EPHB2 has been reported to promote migratory and invasive activity in breast and cervical cancers, whereas its effects are instead inhibitory in colorectal, lung adenocarcinoma and bladder cancers." (PMID 40485734, 2025). "Similarly, a study on cervical cancer showed that miR-204 targeting another gene, EPHB2, affects progression, invasion and migration." (PMID 29382303, 2018). "Consequently, to our knowledge the functional association of receptors including CCR6, EPHB2, NR2C1, and NR2C2 with cervical cancer is being proposed for the first time in this study." (PMID 30020984, 2018). "In addition, ectopic expression of EphB2 in cervical cancer cells results in an increase in cell migration/invasion and EMT signature fibroblast-like morphology, loss of cell-to-cell contact, and downregulation of E-cadherin." (PMID 26356073, 2015). "In addition to cellular movement, our data indicate that similar to cutaneous squamous cell carcinoma cells, cervical cancer cells, and somatic stem cells, EPHB2 enhances the proliferation rate of Schwann cells, supplying new knowledge about the biological activity of EPHB2." (PMID 37949219, 2023). "EPHB2 has been reported to promote in vitro angiogenesis in head and neck cancer and induce EMT in cervical cancer cells." (PMID 32899940, 2020).
Anxiety (9 papers, 2013 to 2025). Intense feelings of nervousness, tension, or panic often arise in response to interpersonal stresses. "Lentiviral vector overexpressed EphB2 injected into the dorsal hippocampus relieved the anxiety-like behaviors." (PMID 28358367, 2017). "Second, neuropsin has been shown to affect stress-induced anxiety by cleaving the extracellular portion of EphB2." (PMID 27701413, 2016). "Neuropsin has been shown to be involved in anxiety following acute stress by regulating the dynamics of the EphB2-NMDA-receptor interaction." (PMID 27701413, 2016). "Overexpression of EphB2 in the basolateral amygdala may enhance synaptic plasticity through upregulating NMDARs, which results in visceral hypersensitivity and anxiety‐like behaviors in rats with psychological stress." (PMID 38353051, 2024). "The data of EPM suggest that EphB2 knockdown in BLA abolishes anxiety‐like behaviors in WAS rats." (PMID 38353051, 2024). "However, activation of NMDARs after the knockdown of EphB2 expression still triggered visceral hypersensitivity and anxiety‐like behaviors." (PMID 38353051, 2024). "However, during the maintenance stage of visceral pain, visceral hypersensitivity was only partially relieved but anxiety‐like behaviors were abolished by inactivation of BLA or downregulation of EphB2 in BLA." (PMID 38353051, 2024). "Previous studies linked EphB2 to the pathology of anxiety and to memory processes since the lack of EphB2 in germline-targeted mice replicated deficiencies in long-term potentiation (LTP) and long-term depression (LTD), as well as behavioral impairments." (PMID 30131699, 2018). "Interestingly, knocking down EphB2 in BLA after WAS model establishment could abolish anxiety‐like behaviors but only partially relieve visceral hypersensitivity during the maintenance stage of chronic visceral pain." (PMID 38353051, 2024). "Inactivation of BLA or downregulation of EphB2 in BLA failed to induce visceral hypersensitivity as well as anxiety‐like behaviors." (PMID 38353051, 2024). "The results suggest that EphB2 knockdown in BLA also fails to induce anxiety‐like behaviors." (PMID 38353051, 2024). "Furthermore, we found knocking down EphB2 in BLA before WAS could abolish the induction of visceral hypersensitivity and anxiety‐like behaviors." (PMID 38353051, 2024).
hepatocellular carcinoma (9 papers, 2014 to 2025). A malignant tumor that arises from hepatocytes. "EphB2 expression was found to be stepwise increased from normal liver tissues to cirrhotic liver tissues and to hepatocellular carcinoma (HCC) tissues and associated with poor prognosis." (PMID 35223830, 2022). "In hepatocellular carcinoma, EPHB2 enhances cancer stem cell properties and drive sorafenib resistance by activating SRC/AKT/GSK3β/β-catenin signaling cascade." (PMID 36032135, 2022). "In human, EphB2 was initially found to be highly upregulated in hepatocellular carcinoma, the end-stage of liver fibrosis/cirrhosis." (PMID 29416088, 2018). "Our previous study showed that different pancreatic cancer cell lines with different levels of erythropoietin-producing hepatoma cell line-B2 (EphB2) expression exhibited different responses to QYHJ treatment." (PMID 24959213, 2014). "Our previous study demonstrated that inhibition of erythropoietin-producing hepatoma cell line-B2 (EphB2) expression resulted in the promotion of cancer growth, with EphB2 acting as a tumor suppressor in pancreatic cancer." (PMID 24959213, 2014).
liver fibrosis (9 papers, 2017 to 2024). "Here, we report that EphB2, a receptor tyrosine kinase previously implicated in liver fibrosis, is regulated by cysteine sulfenylation during the fibrotic progression of liver." (PMID 39164267, 2024). "We and others have previously reported that increased expression of EphB2 is associated with liver fibrosis, and the deficiency of EphB2 by knockout or microRNA can alleviate the development of liver fibrosis." (PMID 36834826, 2023). "Although the dysregulation of Eph receptor tyrosine kinase EphB2 has been reported to associate with the development of liver fibrosis, the involvement of other Eph family members in liver fibrosis remains underexplored." (PMID 36834826, 2023). "We demonstrate that EphB2 is critical for the optimal trans-differentiation of quiescent HSCs into fibrogenic myofibroblasts and accordingly EphB2 deficiency attenuates hepatic fibrosis in mice." (PMID 29416088, 2018). "Although we have previously shown a critical role for the related Eph receptor, EphB2, in the development of malaria-associated liver fibrosis, this study constitutes the first time that any member of this family of Eph receptors has been linked to neurological manifestations of malaria." (PMID 31999807, 2020). "Next, we determined whether the reduction of liver fibrosis in CCl4-treated EphB2−/− mice was also associated with a decrease in pro-inflammatory cytokines and chemokines." (PMID 29416088, 2018). "Moreover, we show that EphB2 deficiency attenuates liver fibrosis and inflammation and this is correlated with an overall reduction in pro-fibrotic markers, inflammatory chemokines and cytokines." (PMID 29416088, 2018). "The profibrogenic roles of EphB2 in liver fibrosis and MASH have been recognized in several different murine models." (PMID 39164267, 2024). "The involvement of EphB2 sulfenylation in the anti-hepatic fibrosis activity of IDE was then investigated." (PMID 39164267, 2024). "Herein, we disclosed the hepatic sulfenylation of EphB2 during the progression of liver fibrosis in both activated HSCs and animal models, and identified the sulfenylation cysteine sites on EphB2." (PMID 39164267, 2024). "Next, we examined the gene expression of EphB2 and several representative profibrotic protein markers during the progression of CCl4-induced liver fibrosis in mice (GSE222567 and GSE135462)." (PMID 39164267, 2024). "Theses analyses strongly suggested significant alterations in gene expression of EphB2 during the progression phase of liver fibrosis and HSC activation." (PMID 39164267, 2024). "The role of EphB2 in promoting HSCs activation and liver fibrosis progression has been well documented." (PMID 36834826, 2023). "We found that EphB2 upregulation is a direct downstream molecular event of decreased expression of miR-451 and miR-185 in the process of liver fibrosis." (PMID 32467578, 2020). "Our findings not only provide new insights about the regulation of EphB2 overexpression in liver fibrosis, but also bring a novel miRNA-based therapeutic strategy for the treatment of hepatic fibrosis." (PMID 32467578, 2020). "These proof-of-concept results further delineate a novel mechanism for upregulation of EphB2 in liver fibrosis and provide a potential therapeutic strategy for treatment of liver fibrosis." (PMID 32467578, 2020). "Restoration of miR-451 and miR-185 at the same time prominently decreased EphB2 protein level, and suppressed liver fibrosis both in vitro and in vivo." (PMID 32467578, 2020). "We found that the activation of HSCs was associated with downregulation of miR-451/miR-185 accompanied by upregulation of EphB2 and other fibrosis markers, which were further confirmed in CCl4-induced hepatic fibrosis models." (PMID 32467578, 2020). "In summary, this study highlights EphB2 as a key fibrogenic molecule involved in the development and progression of hepatic fibrosis." (PMID 29416088, 2018).
liver fibrosis (continued). "Collectively this data suggest that HSCs are potentially the primary cell type that upregulate transcription of EphB2 and Ephrin-B ligands in CCl4-induced liver fibrosis." (PMID 29416088, 2018). "Altogether, this data demonstrates that upregulation of EphB2 is a feature of mouse and human liver fibrosis." (PMID 29416088, 2018). "Here we report that upregulation of EphB2 is a prominent feature of two mouse models of hepatic fibrosis and also observed in humans with liver cirrhosis." (PMID 29416088, 2018). "To determine which cell type within the liver contributes to the observed increase in EphB2 during liver fibrosis we carried out cell fractionation on livers from CCl4-treated and oil-treated mice." (PMID 29416088, 2018). "Compared to similarly treated wild type littermate controls, CCl4-treated EphB2−/− mice had reduced liver fibrosis." (PMID 29416088, 2018). "Our current work in mouse models of hepatic fibrosis have identified EphB2 mRNA transcripts as the most upregulated of the five EphB receptors in fibrotic livers of CCl4 and MDR2-null mice." (PMID 29416088, 2018). "However, it remains not fully explored regarding the regulation of posttranslational modifications (PTMs) other than phosphorylation on the functions and activities of EphB2 during progression of liver fibrosis." (PMID 39164267, 2024). "In conclusion, we demonstrate that EphB2 undergoes sulfenylation during liver fibrosis progression, which enhances its kinase activity, antagonizes its ubiquitination-mediated degradation, promotes its interactions with other proteins, and activates the downstream FAK/MAPK signaling." (PMID 39164267, 2024). "Our findings that both EphB2 sulfenylation and protein levels increased during liver fibrosis suggested that EphB2 sulfenylation might stabilize EphB2 protein." (PMID 39164267, 2024). "Thus, our findings not only advance the understanding of PTMs of EphB2 but also provide a potentially effective strategy for the treatment of liver fibrosis." (PMID 39164267, 2024). "These genes, including Robo1, Gabrb3, Gpc6, Ephb2 and Dlg2, are usually not expressed in healthy liver, and were reported to be upregulated in metabolic dysfunction-associated steatohepatitis and liver fibrosis." (PMID 39456836, 2024). "It has been shown that some Eph receptors can be phosphorylated by other Eph receptors through reciprocal regulation, and whether EphB1 and EphB2 would synergistically contribute to liver fibrosis remains to be explored." (PMID 36834826, 2023). "Recently, several studies reported that EphB2 was abnormally upregulated in mice model of liver fibrosis induced by infection or inflammation, and could be potentially targeted for novel antifibrotic therapies." (PMID 32467578, 2020). "In this study, we investigated whether miR-451/miR-185 is related to liver fibrosis, and probed the relationship between these miRNAs and EphB2 gene." (PMID 32467578, 2020). "However, the detailed mechanism for the upregulation of EphB2 in liver fibrosis remains to be fully elucidated." (PMID 32467578, 2020). "Furthermore, our human biopsy data showing that EphB2 expression is upregulated in liver cirrhosis indicates that these observations have relevance to human liver fibrosis." (PMID 29416088, 2018). "Pending further validation with specific pharmacological inhibitor, EphB2 could potentially be a novel therapeutic target for the treatment of liver fibrosis/cirrhosis." (PMID 29416088, 2018). "However, our preliminary study showed that EphB1 was the only NEDD8-conjugated protein among EphB1 to EphB3 in activated HSCs, suggesting that the activation of EphB1 and the way it functions may be different from EphB2 in liver fibrosis." (PMID 36834826, 2023).
liver fibrosis (continued). "Having shown that EphB2 expression is elevated on HSCs during liver fibrosis and that it is required for TGF-β1 signaling and CCl4-induced hepatic fibrosis in mice, we next hypothesized that EphB2 deficiency could dampen the differentiation of HSCs into fibrogenic myofibroblasts." (PMID 29416088, 2018). "Given that transcription of TGF- β1 was reduced in the livers of CCl4-treated EphB2−/− mice compared to littermates, we determined whether the reduction in liver fibrosis in CCl4-treated EphB2−/− mice could also be resulting from a compromised phosphorylation of SMAD complex on HSCs." (PMID 29416088, 2018). "This supports the hypothesis that EphB2 promotes liver fibrosis partly via activation of HSCs." (PMID 29416088, 2018). "In particular, increased Robo1 and Ephb2 expression has been experimentally proven to promote MASH and liver fibrosis." (PMID 39456836, 2024). "Collectively, this study reveals cysteine sulfenylation as a new type of PTM for EphB2 and sheds a light on the therapeutic potential of IDE for the treatment of liver fibrosis." (PMID 39164267, 2024). "EPHB2 and ANXA2 are related to hepatic fibrosis that is not only a prominent feature of BA but also a good predictor of outcome in mice following portoenterostomy." (PMID 32848883, 2020). "Taken together, these results verified the profibrotic role of EphB2, demonstrated a reduced expression of miR-451/miR-185 during the progression of liver fibrosis, and also revealed a negative relationship between EphB2 and miR-451/miR-185 expression." (PMID 32467578, 2020). "No major change in EphB2 mRNA levels was observed in LSEC or HEP during CCl4-induced liver fibrosis." (PMID 29416088, 2018). "In this report, we provide substantial evidence linking upregulation of EphB2 with liver fibrogenesis in non-pathogen driven mouse models of hepatic fibrosis." (PMID 29416088, 2018). "Having established that EphB2 is the most highly upregulated of the EphB receptors in both the CCl4 and MDR2-null mouse models of hepatic fibrosis, we next determined the human relevance of our findings by screening for EphB2 expression in human biopsies specimen of cirrhotic livers." (PMID 29416088, 2018). "After examination of the EphB2 overexpression in immortalized HSC cell lines, isolated quiescent and activated primary HSCs, and fibrotic liver, we proved that EphB2 upregulation is a downstream molecular event of decreased expression of miR-451 and miR-185 in the process of liver fibrosis." (PMID 32467578, 2020).
melanoma (9 papers, 2017 to 2024). A malignant, usually aggressive tumor composed of atypical, neoplastic melanocytes. "This drug was also found to treat cancers linked to the EphB2-ephrinB2 complex such as melanoma and leukemia." (PMID 33354416, 2020). "Tumours of the human prostate, stomach, colon, and melanoma have all been shown to include alterations in EphB2." (PMID 36830852, 2023). "Of note, several of the other genes with decreased expression upon knockdown of Tfap2a have been reported in the literature as activated (Aldh1a3, Igf2bp1, Ephb2, Pbk) or downregulated (Qpct, Wfdc1) in melanoma." (PMID 28249010, 2017). "Among these kinases, 6 (RPS6KB2, DSTYK, TBRG4, CDK4, POLR2E, FASTKD5) and 4 (STK26, PAK1, EPHB2 and JAK3) were consistently up- or down-regulated, respectively, in the metastatic lines of at least two pairs of melanoma cells." (PMID 32051510, 2020).
memory impairment (9 papers, 2014 to 2024). "In addition, EphB2 dysfunction that causes long-term memory impairment is not mediated by defects in neurogenesis." (PMID 38913115, 2024). "The NMDA receptor is phosphorylated by the C-terminal of EphB2, while reduced processing of EphB2 may decrease the cell surface expression of NMDAR, resulting in learning and memory impairment." (PMID 24756565, 2014).